HGF (hepatocyte growth factor)
Diseases named in the same sentence as HGF in open-access papers (continued):
Sharing a sentence is not in itself a finding about the gene and the disease.
tumor (continued). "Overexpression of HGF and c-MET has been shown to exert its effects in tumor progression in association with RhoA and probably with TIMP-3 in pulmonary non-small-cells which promotes EMT and carcinogenesis via up-regulation of COX-2 and Akt." (PMID 28536400, 2015). "The Slit-Robo interaction inhibits hepatocyte growth factor (HGF)/MET-induced tumor cell migration and invasion." (PMID 26674478, 2015). "Our prior studies have shown that MET inhibitors can effectively impair HGF-autocrine GBM tumor growth." (PMID 26381735, 2015). "Previous studies showed that hypoxia expedited tumor invasion and metastasis by inducing hepatocyte growth factor and hypoxia-inducible factor (HIF)." (PMID 26156021, 2015). "To examine the effects of interplay between Ras inhibition and HGF/SF-Met in vivo, we measured their effects on tumor growth and blood flow." (PMID 25593982, 2014). "HGF-dependent Met activation plays an important role in stimulating epithelial-mesenchymal transition (EMT) in tumor cells, resulting in increased tumor cell proliferation, survival, motility, angiogenesis, invasion, and metastasis." (PMID 26932375, 2014). "HGF and its tyrosine kinase receptor Met are key players in MM carcinogenesis and tumor progression." (PMID 28548074, 2014). "Pim-1 plays a significant role on MET expression, the receptor for hepatocyte growth factor (HGF) involved in signaling normal and tumor cell migration and invasion." (PMID 25491234, 2014). "The aim of this study was to gain a better understanding of the interplay between HGF/SF-Met–Ras signaling, tumor metabolism, and blood flow." (PMID 25593982, 2014). "In MET-dependent preclinical models, it inhibited the growth of both HGF-activated and constitutively phosphorylated tumor cell lines." (PMID 28548076, 2014). "Follistatin was significantly upregulated in tumor stroma, as compared to tumor cells (p < 0.001) while G-CSF, HGF and MMP-2 showed a trend for an increased expression in the stromal compartment." (PMID 25483099, 2014). "In two different studies, HGF was detected in the tumor stroma and in the cytoplasm of some tumor cells, raising the possibility that an HGF/Met autocrine loop can be activated in PTC cells." (PMID 28548071, 2014). "Hepatocarcinoma tumor cells release HGF, which stimulates MET activity, and MET activation in cell amplification promotes activation of PI3K/Akt and ERK signaling." (PMID 25162296, 2014). "In cancer tissues, tumor cells play a role in inducing HGF/SF expression by stromal fibroblasts, whereas fibroblast-derived HGF/SF leads to invasive growth of tumor cells through MET." (PMID 25268161, 2014). "In BALB/c-nu/nu mice receiving the inoculation of 786-0 cells, HGF protein expression in tumor tissues was markedly enhanced by MVs, which was further corroborated by a marked intensification of HGF staining in tumor cells." (PMID 24797571, 2014). "Currently, there is a mounting evidence for the involvement of chronic or dysregulated activation of c-Met receptor tyrosine kinase and its ligand HGF in multiple types of tumor cells leading to enhancing cell growth, angiogenesis, and survival." (PMID 24849787, 2014). "The paracrine activation of c-Met on tumor cells by HGF increases invasion of experimental DCIS lesions in xenografts, for example." (PMID 25011545, 2014). "Inhibition of Ras signaling does not affect glucose consumption or basal tumor blood flow but dramatically decreases ATP synthesis and the HGF/SF induced increase in tumor blood volume." (PMID 25593982, 2014). "The proto-oncogene c-MET is a transmembrane tyrosine kinase cell surface receptor for hepatocyte growth factor (HGF), which is mainly involved in cell proliferation and tumor expansion." (PMID 24884990, 2014). "This Registered Report describes theproposed replication plan of key experiments from ‘Tumour micro-environmentelicits innate resistance to RAF inhibitors through HGF secretion’ byStraussman and colleagues, published in Nature in 2012." (PMID 25490933, 2014).
tumor (continued). "The increased expression of Met in vascular endothelial cells of MM microenvironment and the higher microvessel density in MM overexpressing HGF indicated that a HGF/Met autocrine loop contributed to tumor angiogenesis in MM." (PMID 28548074, 2014). "The inhibitory effects of FTS (40 mg/kg) on basal (vehicle-treated) and on HGF/SF-induced tumor blood volumes were evaluated at different times between 2 hours and 24 hours after treatment." (PMID 25593982, 2014). "When monolayer or spheroid cultures were stimulated with EGF or HGF, all of the tumor cell lines, cultured as 3D spheroids, were less responsive to growth factor stimulation (phosphorylation of EGFR and cMET, respectively) than cells grown as 2D monolayers." (PMID 24638075, 2014). "Ezrin interacts with several cell signaling molecules involved in tumour progression including hepatocyte growth factor (HGF) receptor Met, β4-integrin, and Src family kinases." (PMID 25231728, 2014). "Met content among UC derived cell lines was comparable or greater than that found in many other HGF-responsive tumor-derived cell lines." (PMID 25534569, 2014). "Under hypoxic conditions, silencing of HIF-1β expression suppressed tumor cell growth and regulated the expression of tumor growth-related factors, such as vascular endothelial growth factor, epidermal growth factor, and hepatocyte growth factor." (PMID 25068796, 2014). "In preclinical GEC models, abrogation of HGF/MET signaling has been shown to induce tumor regression as well as inhibition of metastatic dissemination." (PMID 24930887, 2014). "Activation of Met by HGF/SF leads to hemodynamic changes, expressed in a dramatic increase in blood flow to the tumor." (PMID 25593982, 2014). "Hepatocyte growth factor (HGF)/c-Met is a tumor promoting pathway that is significantly activated in BBC patient samples." (PMID 25072025, 2014). "Our observations are consistent with the possibility that HGF stimulation of Met + PTC cells is one of the molecular mechanisms involved in the recruitment of dendritic cells into the tumor." (PMID 28548071, 2014). "Subcutaneously implanted SW780 cells grew significantly faster in hHGF/SCID mice relative to SCID mice, revealing the ability of paracrine delivered HGF to drive UC tumor growth." (PMID 25534569, 2014). "Met tyrosine kinase receptor signaling upon activation by its ligand, hepatocyte growth factor/scatter factor (HGF/SF), increases glycolysis, oxidative phosporylation, oxygen consumption, and tumor blood volume." (PMID 25593982, 2014). "Activation of HGF is indicative of aggressive tumor pathology, including enhanced proliferation and invasion." (PMID 25478227, 2014). "The inhibition was observed as early as 8 hours after FTS treatment (n = 28, P = 0.035) and after 24 hours the observed decrease in HGF/SF-induced tumor blood volume was also significant (n = 26, P = 0.028)." (PMID 25593982, 2014). "This wave emerges in both normal and tumor cells, and is amplified by Met activation with hepatocyte growth factor/scatter factor." (PMID 25058592, 2014). "The cell migration pattern in all the tumor spheroids resembled an amoeboid migration pattern in the presence of HGF, while the A549 and H1650 also showed a radial pattern close to the tumor spheroid." (PMID 24638075, 2014). "These growth factors attract and activate fibroblasts in the tumor region increasing their cell growth and HGF secretion." (PMID 24978438, 2014). "The resulting stromal modifications (increased vessel stability and matrix degradation) are compatible with tumor expansion, stimulated simultaneously by CAFs release of tumor-supportive growth factors, including HGF, EGF, IL-6 and SDF1." (PMID 25303976, 2014). "We previously established that HGF/SF induces in tumor (DA3) migrating cells a backward propagating wave of increased velocity that is associated with shape modification into larger and more elongated cells." (PMID 25058592, 2014).
tumor (continued). "The use of organ-derived molecules (e.g., P-gp, fibroblast growth factor, hepatocyte growth factor) is one important mechanism for cancer cell metastasis, and these mechanisms influence response of metastatic tumor cells to chemo-/radio-therapy." (PMID 25028967, 2014). "In malignant pleural mesothelioma, Li and colleagues assessed the importance of PDGF-AA, FGF-2 and HGF cytokines networks between tumor cells and CAFs." (PMID 24978438, 2014). "A large body of literature established that hepatocyte growth factor (HGF) and its receptor tyrosine kinase Met have a significant role in tumor growth and metastasis and in therapeutic resistance as well." (PMID 28548074, 2014). "Evidence has been provided that HGF/Met protein interaction is one of the molecular mechanisms promoting tumor vascularization in PTC." (PMID 28548071, 2014). "HGF/SF treatment leads to a significant amplification of the magnitude of the wave for DA3 tumor cells throughout the healing process." (PMID 25058592, 2014). "HGF-Met signaling has been reported to interact with various cancer-related molecules that promote tumor growth and metastasis." (PMID 25521854, 2014). "Cabozantinib also significantly inhibited HGF-driven tumor xenograft growth and Met activation in SCID and, more dramatically, in hHGF/SCID mice." (PMID 25534569, 2014). "We and others have shown increased cathepsin B secretion and tumor cell invasion in response to factors within the tumor microenvironment including acidic pHe and HGF." (PMID 24505328, 2014). "Perturbation of HGF/MET signaling with anti-HGF antibodies or MET kinase inhibitors attenuates both tumor growth and metastatic dissemination in both GEC cell lines and animal models." (PMID 24930887, 2014). "Using the Ras inhibitor S-trans,trans-farnesylthiosalicylic acid (FTS), we investigated interplay between HGF/SF-Met–Ras signaling, metabolism, and tumor blood-flow regulation." (PMID 25593982, 2014). "HGF levels were correlated with blood neutrophil counts, a finding consistent with HGF level being the reflection of tumour burden." (PMID 25119536, 2014). "Since c-Met levels were higher in Rab7 knockdown cells, we predicted that these tumor cells would be more responsive to lower concentrations of HGF." (PMID 24505328, 2014). "HGF/Met signaling also enhanced MM cell adhesion and invasion, accompanied by expression of matrix metalloproteinases and serine proteases critical for tumor progression." (PMID 28548074, 2014). "HGF and Met are expressed in MM cells, suggesting that the HGF/Met signaling plays a role in development and progression of this tumor, by autocrine and/or paracrine mechanisms." (PMID 28548074, 2014). "The hepatocyte growth factor (HGF)-Met signaling system plays an important role in tumor growth, invasion, and metastasis in many types of malignancies." (PMID 25521854, 2014). "Of note, among these cytokines, a high level of the hepatocyte growth factor (HGF), released during tumor transformation of the mesothelial cells, was detected for the first time in sera of MM patients SV40 infected." (PMID 25162674, 2014). "HGF protein content in bladder tissue extracts and urine were found to correlate significantly with tumor stage and grade." (PMID 25534569, 2014). "We also showed that Met activation induces an increase in tumor blood flow as early as 20 minutes after HGF/SF administration, pointing to recoupling of metabolism and blood flow." (PMID 25593982, 2014). "For that concerning HGF, staining was present in both tumor and macrophages and, similarly, c-Met expression in both tumor and stromal cells." (PMID 24952592, 2014). "Alternatively, galectin-7 mediates the nuclear export of Smad3 through complex formation, which is essential for the tumor-suppressive effects of hepatocyte growth factor on the transforming growth factor-beta signaling pathway." (PMID 24515895, 2014).
tumor (continued). "In a previous study we showed that HGF/SF treatment in vivo leads to an increase of 200% to 300% in tumor blood volume." (PMID 25593982, 2014). "In fact, HGF induces tumor cells to release chemokines active in the recruitment of dendritic cells, and is involved in regulating the production of proangiogenic factors." (PMID 28548071, 2014). "In mice treated with either low-dose (n = 18) or high-dose (n = 21) FTS, the HGF/SF-induced increase in tumor blood volume was significantly inhibited (P = 0.036;,P = 0.0002, respectively)." (PMID 25593982, 2014). "The hepatocyte growth factor (HGF)-Met signaling axis is an important regulator of tumor cell invasion and metastasis." (PMID 24505328, 2014). "Western blot analysis also revealed that the addition of MVs led to a marked increase of HGF protein expression in tumor tissues." (PMID 24797571, 2014). "HGF is also a strong inducer of tumor growth, angiogenesis and lymphangiogenesis, thereby promoting invasion and metastasis of tumor cells." (PMID 24595237, 2014). "As a result, HGF decreases the trans-endothelial resistance of tumor vessels, and then cancer invasion across an EC barrier (i.e., intra-vasation) is achieved." (PMID 23296269, 2013). "HGF/cMET pathway was shown to provide tumor cells with a proliferative advantage, through the tyrosine phosphorylation of the focal adhesion kinase (FAK) and the downstream activation of cell proliferation, survival, and migration." (PMID 24005867, 2013). "Using NK4 in a mouse model of carcinoma, we firstly found in 1998 that MET inhibition by an HGF-antagonist inhibits tumor invasive growth in vivo." (PMID 23296269, 2013). "Continued administration of the VEGF inhibitor sunitinib increased HGF expression in a murine tumor model, and sunitinib was ineffective when HGF was co-administered." (PMID 24205338, 2013). "In tumor tissues, stroma-secreted HGF is required for cancer cells to infiltrate neighboring tissues, such as vascular beds, across the basement membrane." (PMID 23296269, 2013). "When subcutaneously implanted into mice, tumors produced HGF (7.4±2.71 ng/ml: average of 10 animals), which was further confirmed ex vivo, in tumor lysates." (PMID 23812422, 2013). "The systemic expression of pro-HGF suppresses tumor growth and prevents metastatic dissemination in mice." (PMID 23296269, 2013). "Prior to referring to the successful results of NK4 in rodents, the mechanisms of HGF-mediated tumor metastasis will be discussed." (PMID 23296269, 2013). "It has been 15 years since NK4 was identified in 1997 as an HGF-antagonist that inhibits tumor-stroma interaction during metastasis." (PMID 23296269, 2013). "In the ESCC tissues, positive staining of TGFβ1 and HGF was observed in stromal fibroblasts and inflammatory cells adjacent to tumour cells, particularly at the invasive edges of tumours." (PMID 24137336, 2013). "HGF overexpression appears to be related to the invasion and migration of tumor cells, mainly through the p42/p44 MAPK pathway, which enhances cellular proliferation, promoting the EMT." (PMID 24005867, 2013). "Many studies demonstrate that hepatocyte growth factor- (HGF-) Met axis plays an important role in tumor progression and drug sensitivity." (PMID 23533466, 2013). "HGF has been reported to play critical roles in proliferation, migration, invasion, tumor angiogenesis, and lymphangiogenesis, recently." (PMID 23320110, 2013). "Exogenous signals such as epidermal growth factor (EGF) and hepatocyte growth factor (HGF) were previously reported to be vital to maintain sustained growth of tumor cells by binding to their receptors." (PMID 24205104, 2013). "In a different study, the effect of hepatocyte growth factor (HGF) on tumor invasion was examined in U2-OS and SiHa cells." (PMID 23294542, 2013). "Our studies show that these CTCs have increased expression of HGF and c-Met in comparison to the primary tumor cells." (PMID 23723997, 2013).
tumor (continued). "Human HGF measured in the tumors was strongly reduced in the MetHer1 treatment group compared with the vehicle group, probably as a consequence of smaller tumor sizes." (PMID 23812422, 2013). "During tumor cell motility, HGF stimulates the Ras-Rab5 cascade for initiating endocytosis of cadherins, followed by nuclear localization of β-catenin, a transcription factor of genes required for cell motility." (PMID 23296269, 2013). "Aspirin is a classic type COX2 inhibitor that reduces tumor malignancy via an inhibition of prostaglandin-dependent HGF production." (PMID 23296269, 2013). "Some clones of monoclonal antibodies against HGF were screened in vitro and anti-tumor efficacy was evaluated in human cancer-bearing nude mice." (PMID 23296269, 2013). "HGF protein belongs to the plasminogen-related growth factor family and it is expressed by cells of mesenchymal origin or by tumor cells through autocrine mechanism." (PMID 24005867, 2013). "MET/HGF overexpression patterns have been reported to correlate with increased tumor growth rate and metastasis and overall poor prognosis." (PMID 24378750, 2013). "MET, the receptor for hepatocyte growth factor (HGF), is a central mediator of tumor cell growth, survival and motility." (PMID 23516391, 2013). "In the same year, another group also demonstrated the anti-tumor effect of anti-HGF antibody in a xeno-graft model." (PMID 23296269, 2013). "Using NK4 in this model, we provided the first evidence that HGF- antagonist can arrest tumor invasion in vivo: recombinant NK4 inhibited the growth and muscular invasion in mice bearing GB-d1 carcinoma." (PMID 23296269, 2013). "Inhibition of prostaglandin-E synthesis by indomethacin leads to downregulation of HGF production and suppression of tumor migration, indicating that cancer-derived prostaglandins are important for stromal HGF production." (PMID 23296269, 2013). "In the tumor area, a strong signal of HGF and slight staining of VEGF wasdetected, while zonulin/prehaptoglobin-2 and claudin-5 strongly marked the cell borders ofsurrounding vessels (arrows)." (PMID 23637756, 2013). "HGF stimulates the growth of some tumor cell lines, whereas HGF inhibits the growth of a number of other tumor cell lines." (PMID 23667593, 2013). "Hepatocyte growth factor (HGF) is a glycoprotein secreted by a variety of mesenchymal or tumor cells, which promote migration, invasion, wound healing and survival and suppress apoptosis by c-Met." (PMID 24325214, 2013). "One study showed that neutrophils enhance tumor invasion via paracrine regulation mediated by neutrophil-derived hepatocyte growth factor." (PMID 23409924, 2013). "Because the HGF/c-Met signaling axis affects the activity of the MT-destabilizing protein Stathmin in different tumor cell lines, the effects of HGF on Stathmin expression and phosphorylation were analyzed in primary human keratinocytes." (PMID 24066165, 2013). "It was found that HGF induced resistance to reversible, irreversible, and even mutant-selective EGFR-TKIs by restoring MetGab1/PI3K/Akt pathway, indicating that HGF is an important therapeutic target for overcoming tumor resistance to EGFR-TKIs." (PMID 23533466, 2013). "Studies have demonstrated that CAFs are significant promoters of tumour growth and progression via growth factors, including TGFβ1 and HGF, which are secreted by the CAFs themselves and/or by carcinoma cells." (PMID 24137336, 2013). "In NPC, HGF/SF is abundantly expressed in the interstitial tissues surrounding the tumor, whereas Met is expressed in LMP1-expressing NPC tumor cells." (PMID 24340011, 2013). "The altered fibroblasts produced TGFα and hepatocyte growth factor (HGF) which resulted in accelerated tumour cell growth." (PMID 24090133, 2013).